CEACAM1 (CEA cell adhesion molecule 1)
Diseases named in the same sentence as CEACAM1 in open-access papers (continued):
Sharing a sentence is not in itself a finding about the gene and the disease.
ovarian carcinoma (5 papers, 2018 to 2025). A malignant neoplasm originating from the surface ovarian epithelium. "The present data show for the first time a significant association of CEACAM1 expression with disease outcome in ovarian cancer." (PMID 30050594, 2018). "Another study identified CEACAM1 expression on some highly activated Tregs in the tumor microenvironment of patients with renal cell carcinoma or ovarian cancer." (PMID 40773294, 2025). "High expression of CEACAM1 correlates with better prognosis in advanced ovarian cancer patients, suggesting a tumor suppressor function in ovarian cancer." (PMID 33075095, 2020). "In line with prior results, we observed a primarily membranous CEACAM1 staining in most analyzed ovarian cancer samples together with a weak cytoplasmic expression." (PMID 30050594, 2018). "In order to deeply evaluate the relevance of CEACAM1 for ovarian cancer progression, we analyzed its predictive and prognostic value at both the mRNA and protein level in two well-characterized ovarian cancer cohorts." (PMID 30050594, 2018). "Regarding the primary ovarian carcinoma samples, all cases were divided into two groups with CEACAM1 expression below/above the median value for statistical analysis." (PMID 30050594, 2018). "Our results show a strong CEACAM1 expression in most ovarian cancer tissue samples, whereas its impact on prognosis points to a tumor suppressor function." (PMID 30050594, 2018). "Kaplan–Meier analysis revealed a significant association of high CEACAM1 levels with a longer recurrence-free survival (p = 0.035) and overall survival (p = 0.004) indicating that CEACAM1 might function as a tumor suppressor in ovarian carcinomas." (PMID 30050594, 2018). "In order to validate the prognostic significance of CEACAM1 expression on a protein level, Western blot analysis was performed in tissue samples from our clinic, including 210 primary ovarian carcinomas, 12 recurrent tumors, 16 borderline tumors, and 4 cystadenomas." (PMID 30050594, 2018). "High CEACAM1 expression significantly correlates with longer recurrence-free and overall survival as shown at mRNA and protein levels in two independent cohorts comprising material from 517 and 210 ovarian cancer patients, respectively." (PMID 30050594, 2018). "Using this PCR procedure in a representative group of 13 samples, we found that ovarian cancer tissue expresses primarily both 4L and the 4S isoforms of CEACAM1, whereas a very weak or no detection of the CEACAM1-3L and -3S variants was observed." (PMID 30050594, 2018). "Although CEACAM1 expression does not correlate with the mode of OvCa metastasis, its relevance for patient outcome strongly differs between both ovarian cancer types." (PMID 30050594, 2018). "In contrast, in normal fallopian tube epithelium, which is considered to be the precursor tissue of most high-grade ovarian carcinomas, CEACAM1 expression was not detectable." (PMID 30050594, 2018). "Remarkably, the correlation between high CEACAM1 protein levels and longer recurrence-free or overall survival was highly significant only within the subpopulation of ovarian cancer patients with solely intraperitoneal metastasis without nodal involvement." (PMID 30050594, 2018). "In contrast, the described proinvasive and promigratory function of CEACAM1 seems to be not as relevant in ovarian cancer." (PMID 30050594, 2018).
gonococcal infection (4 papers, 2007 to 2020). "Due to its close relatedness with the ITIM-bearing gonococcal receptor CEACAM1 it can act as decoy receptor for Neisserial pathogens and is able to induce clearance of gonococcal infections by granulocytes." (PMID 17945019, 2007). "Phase variable Opa protein-dependent binding to CEACAM1 expressed by DCs can also effectively suppress their maturation in response to activating stimuli including gonococcal infection, preventing the cells from stimulating both CD4+ T cell and CD8+ T cell responses." (PMID 32582133, 2020). "Interestingly, CEACAM-1 has been shown to be upregulated in primary ovarian surface epithelial cells by gonococcal infection suggesting that the interaction with this receptor has in vivo relevance." (PMID 19300516, 2009). "The Opa-CEACAM1 dependent effects on DC and T cell effector function would presumably contribute to the absence of effective adaptive memory responses in response to gonorrhea, impacting CD4+ T cells’ role in the adaptive response and CD8+ T cell-mediated killing of N. gonorrhoeae infected cells." (PMID 23424672, 2013). "While the reduced inflammation and absence of memory response may both facilitate gonococcal infection, their cumulative effect on HIV-1 infection and immunity are difficult to test given that gonococcal Opa proteins only bind human (and not mouse or other) CEACAM1." (PMID 32582133, 2020).
lung diseases (4 papers, 2019 to 2024). "The present study aims at evaluating the expression of CEACAM1 in lung diseases and the profiling of CEACAM1 isoforms and PI3K subtypes after IFN-γ treatment, and investigating the role of PI3K pathway in IFN-γ-induced CEACAM1 expression in airway epithelial cells." (PMID 31072323, 2019). "A recent study demonstrated that nine genes (CD274, CEACAM1, CR1, FCGR1A/B, IFITM1, IRAK3, LILRA6, MAPK14, and PDCD1LG2) showed 100% sensitivity and specificity that distinguished patients with active TB from those with other lung diseases (OPD)." (PMID 38674369, 2024).
lymphoma (4 papers, 2011 to 2025). A malignant (clonal) proliferation of B- lymphocytes or T- lymphocytes which involves the lymph nodes, bone marrow and/or extranodal sites. "To expand the library screen results, we selected a small-hairpin RNA (shRNA) to knock down CEACAM1 and transduced it into multiple lymphoma cell lines." (PMID 40436855, 2025). "We next evaluated the correlation between CEACAM1 expression in lymphoma cells and their response to ibrutinib, which inhibits the BCR pathway kinase BTK." (PMID 40436855, 2025). "CEACAM1 was found to intensely stain the surface of the lymphoma cells from a majority of primary MCL biopsies (86.9%) and CLL/SLL (93.7%), and some cases of DLBCL (25.6%), follicular lymphoma (FL) (31.3%), and classical Hodgkin lymphoma (cHL) (7.7%)." (PMID 40436855, 2025). "When analyzing the target cells for the expression of the membrane-bound ligand of TIM-3, CEACAM1, we observed that many leukemia and lymphoma cell lines upregulate CEACAM1 when exposed to Th1 cytokines IFN-γ and TNF-α." (PMID 35464394, 2022). "Although both A20 lymphoma and renal cell carcinoma express Ceacam1, A20 cells uniformly expressed Ceacam1 at high levels, while only a subset of RENCA cells showed (somewhat lower) expression." (PMID 21760897, 2011). "When we analyzed these two tumor lines for Ceacam1 expression, we noted that all A20 lymphoma cells uniformly expressed high levels, while only a subset of RENCA cells expressed some Ceacam1." (PMID 21760897, 2011). "Recipients of Ceacam1−/− donor T cells had improved survival in the A20 lymphoma model, but both T cell replete groups showed comparable survival in the RENCA solid tumor model." (PMID 21760897, 2011). "Finally, we assessed the GVT activity of Ceacam1−/− donor alloreactive T cells against A20 lymphoma and RENCA renal cell carcinoma." (PMID 21760897, 2011). "Finally, graft-versus-tumor survival in a Ceacam1+ lymphoma model was improved in animals receiving Ceacam1−/− vs. control T cells." (PMID 21760897, 2011). "Lymphoma cells with high CEACAM1 expression were found to be more sensitive to ibrutinib than those with low expression levels, except for MAVER-1 cells, which had high CEACAM1 expression but were resistant to ibrutinib (see Discussion)." (PMID 40436855, 2025). "Collectively, these findings indicate that CEACAM1 not only plays an activating role but can also act as a negative regulator of BCR signaling in lymphoma cells with low or absent CEACAM1 expression by preferentially binding to SHP-1 instead of SYK." (PMID 40436855, 2025). "We were interested to note that in our GVT experiments, recipients of Ceacam1−/− T cells had significantly improved survival when challenged with A20 lymphoma but not renal cell carcinoma." (PMID 21760897, 2011). "The strong correlation between CEACAM1 expression levels and the BCR signature in MCL tumors, and its relationship to ibrutinib responsiveness in MCL and MZL cell lines, suggests a potential utility of CEACAM1 as a biomarker of ibrutinib therapy in these lymphomas." (PMID 40436855, 2025).
non-alcoholic fatty liver disease (4 papers, 2017 to 2023). "Obese insulin-resistant humans with non-alcoholic fatty liver disease manifest loss of hepatic CEACAM1." (PMID 30314283, 2018).
renal cell carcinoma (4 papers, 2011 to 2025). "Since TIM-3, which binds to CEACAM1, are expressed in immune cells such as CD4+ and CD8+ T lymphocytes, CEACAM1 may play an important role in mediating immune cell infiltration in renal cell carcinoma." (PMID 36712923, 2023). "Therefore, understanding the relationship between CEACAM1 and tumor immune cell infiltration is of great importance, and CEACAM1 may become an attractive target for immunotherapy in renal cell carcinoma." (PMID 36712923, 2023).
rheumatoid arthritis (4 papers, 2022 to 2025). A chronic, systemic autoimmune disorder characterized by inflammation in the synovial membranes and articular surfaces. "Besides, in the rheumatoid arthritis, the AUC values for CEBPA, CEACAM1, BTG3, and IL1R1 were 0.609, 0.730, 0.686, and 0.608, respectively and diagnostic model achieved a high AUC of 0.844 on this cohort." (PMID 39113685, 2024).
Autoimmunity (3 papers, 2016 to 2024). The occurrence of an immune reaction against the organism's own cells or tissues. "The interaction between TIM-3 and CEACAM1 unveils a sophisticated regulatory network that impacts both autoimmunity and anti-tumor immunity." (PMID 38646539, 2024). "This intricate interplay between TIM-3 and CEACAM1 holds significant implications for modulating immune responses in the context of cancer and autoimmune disorders." (PMID 38646539, 2024). "Taken together, our data are promising for the establishment of new and more specific therapeutic strategies in MS that target CEACAM1 and thereby reduce the detrimental effects of B cell-mediated autoimmunity in the CNS." (PMID 27435215, 2016). "Recently, it was demonstrated that CEACAM1 serves as a heterophilic ligand for TIM–3 in activated T cells and that this interaction is crucial for regulating autoimmunity." (PMID 36591283, 2022).
B-cell lymphoma (3 papers, 2011 to 2025). "Flow cytometric analysis also revealed high levels of CEACAM1 surface expression on MCL PDX models and primary MCL samples compared to other B-cell lymphoma or CD19+ naïve B cells." (PMID 40436855, 2025). "Ceacam1−/− CD8 T cells and WT CD8 T cells demonstrated similar cytolysis against 51Cr-radiolabeled allogeneic A20 B cell lymphoma cells and EL4 controls." (PMID 21760897, 2011).
breast tumors (3 papers, 2014 to 2022). "Tumor xenografts were used to evaluate CEACAM1 isoform expression on the leading edge of breast tumor cells." (PMID 24650050, 2014). "We conclude that differences between long and short cytoplasmic isoforms occur in human breast tumor CEACAM1 expressing cells, and are influenced by the tumor microenvironment, and specifically, favor the long isoform characteristic of immune cells rather than the normal epithelial short isoform." (PMID 24650050, 2014). "For example, events in CYB561 and CEACAM1 are enriched in HER2+, and E2F4, AP2A2, MGAT4B, and DUXAP9 events are enriched in basal-like breast tumors." (PMID 35044822, 2022). "Moreover, CEACAM1, as opposed to CEACAM3, acts as a tumor suppressor, shown to inhibit the growth of prostate, colon, and breast tumors." (PMID 24858421, 2014).
cervical carcinoma (3 papers, 2007 to 2023). A carcinoma arising from either the exocervical squamous epithelium or the endocervical glandular epithelium. "We observed that CD274, CEACAM1, LGALS9, PVR and TNFRSF14 were significantly different (P < 0.05) between two groups, providing a novel insight into immunotherapy for cervical carcinoma patients." (PMID 34789197, 2021). "Another member of this gene family, CEACAM1, is shown to have no or very low expression in cervical carcinoma." (PMID 17543121, 2007).
colonic adenocarcinomas (3 papers, 2016 to 2024). "Here, absence of CEACAM1 in murine colonic adenocarcinomas led to enhanced nuclear translocation of β-catenin." (PMID 27572314, 2016).
gastritis (3 papers, 2021 to 2024). Inflammation of the stomach. "In relation to HopQ specifically, CEACAM1, CEACAM5 and CEACAM6 are all upregulated in gastritis caused by chronic H. pylori infection, again suggesting a mechanism for H. pylori promoting its own persistence in an inflammatory environment." (PMID 38615147, 2024). "However, CEACAM1 expression was induced in H. pylori-induced gastritis as well as in gastric tumors." (PMID 34442827, 2021).
influenza (3 papers, 2016 to 2025). An acute viral infection of the respiratory tract, occurring in isolated cases, in epidemics, or in pandemics; it is caused by serologically different strains of viruses (influenzaviruses) designated A, B, and C, has a 3-day incubation period, and usually lasts for 3 to 10 days. "In order to understand the role of CEACAM1 in influenza pathogenesis, A549 and ATII cells were transfected with siCEACAM1 to knockdown endogenous CEACAM1 protein expression." (PMID 30341336, 2018). "Taken together, these observations suggest that CEACAM1 is an attractive candidate for modulating influenza-specific immunity." (PMID 30341336, 2018). "We recently demonstrated that upon sensing of influenza by RIG-I and HCMV by IFI16, CEACAM1 expression is induced." (PMID 27634893, 2016).
mammary adenocarcinomas (3 papers, 2016 to 2019). "We analyzed the molecular basis for carcinoembryonic antigen-related cell adhesion molecule 1 (CEACAM1)-controlled inhibition of epithelial-mesenchymal transition (EMT) in a mouse model for mammary adenocarcinoma (WAP-T mice)." (PMID 27572314, 2016). "Loss of CEACAM1 in WAP-T tumor cells produced increased canonical Wnt signaling and promoted cellular invasiveness in vitro, and importantly, dramatically enhanced the metastasis rate of mammary adenocarcinomas in CEACAM1null mice in vivo." (PMID 27572314, 2016).
metastatic disease (3 papers, 2006 to 2021). "Immune escape and metastatic disease are associated with increased CEACAM1, an intercellular adhesion protein that has immune modulation functions." (PMID 34066966, 2021).
myocardial infarction (3 papers, 2016 to 2022). Gross necrosis of the myocardium, as a result of interruption of the blood supply to the area, as in coronary thrombosis. "We aims to investigate whether CEACAM1 influences cardiac remodeling in mice with myocardial infarction (MI) and hypoxia-induced cardiomyocyte injury." (PMID 26911181, 2016).
non-alcoholic steatohepatitis (3 papers, 2011 to 2023). "In the liver, loss of CEACAM1 in a murine model has been found to lead to inflammation and Non-Alcoholic Steatohepatitis (NASH), with reduced insulin clearance and altered metabolism." (PMID 36741860, 2023).
pancreatic adenocarcinoma (3 papers, 2016 to 2024). "CEACAM1 also distinguished between chronic pancreatitis and pancreatic adenocarcinoma patients with an AUC of 0.752." (PMID 35454771, 2022). "CEACAM1 is a cell adhesion molecule that is present in epithelial cells throughout the body and has been shown to localize to neoplastic epithelial cells in pancreatic adenocarcinoma." (PMID 38291365, 2024).
periodontitis (3 papers, 2022 to 2025). An acute or chronic inflammatory process that affects the tissues that surround and support the teeth. "However, the protein expression of Ceacam1 in periodontitis, the role of Ceacam1 in alveolar bone remodeling, and the interaction between Ceacam1 and CD47 were not examined in the present study." (PMID 38549147, 2024).
psoriasis (3 papers, 2021 to 2025). An autoimmune condition characterized by red, well-delineated plaques with silvery scales that are usually on the extensor surfaces and scalp. "In psoriasis lesions, CEACAM1 is expressed in keratinocytes, which are localized at the uppermost layer of the epidermis together with neutrophils, and are considered to contribute to the persistence of neutrophils and inflammation in psoriatic skin." (PMID 34639156, 2021).
squamous cell carcinoma (3 papers, 2013 to 2022). A carcinoma arising from squamous epithelial cells. "What need to be noted is that there was a CEACAM1 expression shift from membrane to cytoplasm from well differentiated to poorly differentiated squamous cell carcinoma." (PMID 34368221, 2021). "Our results indicated that membranous expression pattern of CEACAM1 might function as a tumor suppressor in well differentiated squamous cell carcinoma." (PMID 34368221, 2021). "In addition, patients with adenocarcinoma showed higher CEACAM1 mRNA levels than squamous cell carcinoma or other types (P = 0.003)." (PMID 23885995, 2013).
systemic lupus erythematosus (3 papers, 2022 to 2025). An autoimmune multi-organ disease typically associated with vasculopathy and autoantibody production. "miR-31 also inhibits carcinoembryonic antigen related cell adhesion molecule 1 (CEACAM1)-S, which represses Treg development in a model of murine liver autoimmunity but promotes Treg development in peripheral blood mononuclear cells (PBMCs) isolated from systemic lupus erythematosus (SLE) patients." (PMID 36032083, 2022).
thymoma (3 papers, 2016 to 2021). A neoplasm arising from the epithelial cells of the thymus. "For this aim, we used a reporter system that consists of murine thymoma BW cells that were transfected with chimeric proteins composed of the extracellular domain of CEACAM1 fused to a mouse zeta chain." (PMID 34395310, 2021). "In this system, mouse thymoma BW cells expressing chimeric CEACAM1 composed of the extracellular portion of human CEACAM1 fused to the mouse CD3ζ chain secrete mouse IL-2 upon binding and activation of CEACAM1 by specific ligands." (PMID 34336716, 2021). "To test whether the HMPV-mediated CEACAM1 induction has functional consequences we used a cell-based reporter assay that employs the murine BW thymoma cells." (PMID 27634893, 2016).
autoimmune hepatitis (2 papers, 2018 to 2025). Hepatitis caused by autoantibodies. "Research has indicated that CEACAM1 deficiency exacerbates liver inflammation in a mouse model of autoimmune hepatitis." (PMID 40708539, 2025).
bladder tumors (2 papers, 2018 to 2020). "As for invasive bladder tumors, all cases showed CEACAM1-positive blood vessels in close association with the tumor cell groups, with few tumoral cells and neighboring normal urothelial area still exhibiting CEACAM1 expression." (PMID 30406153, 2018). "Our results also showed reduced CEACAM-1 in Bladder tumour cells compared to other tissues." (PMID 33238953, 2020). "There was significantly increased expression of CD31 (p < 0.001), HER-2 (p = 0.032), S100P (p < 0.001), COX-2 (p < 0.001), VEGFR-3 (p < 0.001) and decreased expression of thrombomodulin (p = 0.010) and CEACAM-1 (p < 0.001) in bladder tumours compared to normal bladder tissues." (PMID 33238953, 2020).
brain tumor (2 papers, 2021). "We hypothesized that AQP4 could also be the regulatory factors of various immune checkpoints in brain tumors, such as TIM-3 (HAVCR2), PD-L1 (CD274), PD-L2 (PDCD1LG2), and CEACAM1." (PMID 34113257, 2021).